GPR75 (G protein-coupled receptor 75)
Description:
G protein-coupled receptor that is activated by the chemokine CCL5/RANTES. Probably coupled to heterotrimeric Gq proteins, it stimulates inositol trisphosphate production and calcium mobilization upon activation. Together with CCL5/RANTES, may play a role in neuron survival through activation of a downstream signaling pathway involving the PI3, Akt and MAP kinases. CCL5/RANTES may also regulate insulin secretion by pancreatic islet cells through activation of this receptor.
Synonyms: WI-31133; GPRchr2; WI31133
Tractability: Small molecule: it belongs to a druggable protein family. Antibody: its Gene Ontology location is reachable by antibodies, with high confidence; UniProt places it where antibodies can reach, with medium confidence; UniProt predicts a signal peptide or a membrane-spanning region.
Target class: Family A G protein-coupled receptor; Membrane receptor
Gene: Protein-coding gene on chromosome 2 (53,852,912 to 53,859,967, reverse strand). Ensembl gene ENSG00000119737.
Subcellular location: Cell membrane
Subcellular location (Human Protein Atlas): Plasma membrane; Primary cilium; Vesicles
Gene Ontology:
Molecular function: C-C chemokine receptor activity; G protein-coupled receptor activity
Biological process: chemokine-mediated signaling pathway; G protein-coupled receptor signaling pathway
Cellular component: plasma membrane; membrane
Genetic constraint (gnomAD): Loss-of-function variants: 32 observed, 30.82 expected, observed/expected ratio (o/e) 1.04, 90% interval 0.78 to 1.39. The upper end of that interval is the gene's LOEUF score, 1.39, which puts it in group 5 of 6, group 1 being the genes least tolerant of losing a copy. Missense variants: 699 observed, 700.17 expected, observed/expected ratio (o/e) 1, 90% interval 0.94 to 1.06. Synonymous variants: 285 observed, 270.76 expected, observed/expected ratio (o/e) 1.05, 90% interval 0.95 to 1.16.
Homologues: Orthologues: macaque GPR75 (99% identical), rabbit GPR75 (94% identical), pig GPR75 (94% identical), mouse Gpr75 (88% identical), rat Gpr75 (88% identical), guinea pig GPR75 (86% identical), tropical clawed frog gpr75 (80% identical), zebrafish gpr75 (67% identical), dog GPR75 (60% identical). Paralogues in human: TACR3 (16% identical), TACR1 (15% identical), GPR83 (14% identical), NPY2R (14% identical), MTNR1A (13% identical), TACR2 (13% identical), NPY1R (13% identical), PRLHR (13% identical), OR11G2 (13% identical), MTNR1B (12% identical), OR11H4 (12% identical), OR11H2 (12% identical), and 21 more.
Diseases named in the same sentence as GPR75 in open-access papers:
GPR75 is named in the same sentence as 40 diseases in open-access papers, as found by Europe PMC text mining. Sharing a sentence is not in itself a finding about the gene and the disease. The quoted sentences say what the papers report.
Obesity (19 papers, 2021 to 2026). Accumulation of substantial excess body fat. "Loss of function G-protein coupled receptor 75 (GPR75) variants in humans are associated with leanness, and Gpr75 null mice are protected from diet-induced obesity (DIO)." (PMID 41707065, 2026). "It has been shown that the GPR75 has an important role in glycemic control and insulin sensitivity, and loss-of-function mutations of GPR75 are protective against obesity." (PMID 40342327, 2025). "The situation in polygenic obesity is considerably more complex, although a recent exome sequencing study identifying obesity-protective variants in the GPR75 gene is a promising discovery with therapeutic potential." (PMID 38849463, 2025). "Patients with truncating variants in GPR75 exhibit lower body-mass index BMI and a 54% lower odds ratio toward obesity in the heterozygous state." (PMID 39959811, 2024). "At the same time, the various human GPR75 variants are protected from obesity, metabolic syndrome, and steatosis." (PMID 39959811, 2024). "In contrast to the obesity phenotype associated with many cilia-associated proteins, the leanness observed in Gpr75–/– mice was relatively weak under a chow diet." (PMID 39137039, 2024). "In 2021, the WES association study of more than 640,000 humans with body mass index (BMI) identified the rare LOF in GPR75 as being associated with obesity prevention." (PMID 38344397, 2024). "In summary, the close association of GPR75 deficiency with obesity and food intake in both mice and humans makes it a promising drug target for treating obesity." (PMID 39137039, 2024). "Variants in one of our significant S-PrediXcan genes, GPR75, have been recently shown to have a protective effect against obesity, and have been associated with lower body weight overall." (PMID 35379376, 2022). "We crossed Gpr75–/– mice with Lepob-mutant mice to determine whether GPR75 is involved in leptin signaling and whether loss of GPR75 would attenuate the obesity phenotype of Lepob-mutant mice." (PMID 39137039, 2024). "Examples of other protective variants include the N352S variant in B4GALT1 which is protective against cardiovascular disease and protein-truncating variants in GPR75 which reduce the risk of obesity, as well as the A88V variant in Gjb6, which protects against hearing loss in mice." (PMID 37163093, 2023). "With respect to the available findings, GPR75 is a prominent player in the control of metabolism and glucose homeostasis, and may also be a novel therapeutic target to combat metabolic disorders caused by obesity." (PMID 38344397, 2024). "Recently, AstraZeneca and Regeneron initiated a collaboration to develop GPR75-targeting gene-silencing drugs, monoclonal antibodies, and small-molecule modulators aimed at preventing obesity and its related complications." (PMID 40362321, 2025). "Protein-truncating variants in GPR75 have been linked to lower BMI, and Gpr75–/– mice have shown resistance to HFD-induced obesity." (PMID 39137039, 2024). "In conclusion, GPR75 is a potentially biologically and pharmacologically significant receptor that plays a crucial role in many diseases such as obesity, cancer and metabolic syndrome." (PMID 38344397, 2024). "Alnylam Pharmaceuticals, Inc. has conducted research on siRNA drugs targeting GPR75 mRNA for the prevention and treatment of weight disorders, such as obesity and related diseases." (PMID 38344397, 2024). "Ultimately, these studies demonstrate the role of GPR75 in preventing obesity and MASLD in vivo by maintaining energy balance." (PMID 39310267, 2024). "Regeneron Pharmaceuticals, Inc. is targeting GPR75 to develop a method to inhibit its expression using ASO or the CRIPSR/Cas system in hopes of treating obesity." (PMID 38344397, 2024). "Fortunately, Regeneron has now partnered with AstraZeneca to develop small molecule therapies for GPR75,275 aimed at treating obesity and related complications." (PMID 38344397, 2024).
Obesity (continued). "Results indicated a 25% reduction in weight gain in GPR75 heterozygous mice and a 45% reduction in weight gain in complete gene knockout mice, marking the first in vivo evidence of GPR75's anti-obesity effects." (PMID 39310267, 2024). "In an attempt to solve the lack of combat methods, scientists tried to analyze receptor GPR75 (G Protein Receptor), a new target for the treatment of obesity, using an intracellular nanobody." (PMID 37375810, 2023). "The development of GPR75 agonists or antagonists may lead to major advances in the treatment of obesity, cancer, Alzheimer’s disease, cardiovascular disorders, and other conditions." (PMID 40362321, 2025). "Inhibition of GPR75's may have beneficial effects on diverse diseases including cerebrovascular disease, cardiovascular disease, diabetes, cancer, and obesity." (PMID 38344397, 2024). "Taken together, these findings demonstrate that loss of Gpr75 did not attenuate the obesity phenotype of Lepob- or Adcy3-mutant mice." (PMID 39137039, 2024). "Subsequent investigations using GPR75 gene knockout mice have demonstrated resistance to obesity." (PMID 39232780, 2024). "Further studies are essential to identify the specific ligand for GPR75 in the context of obesity." (PMID 39137039, 2024). "Loss of GPR75 selectively inhibited weight gain in HFD-fed mice but failed to suppress the development of obesity in leptin ob–mutant (Lepob-mutant) mice and adenylate cyclase 3–mutant (Adcy3-mutant) mice on a chow diet." (PMID 39137039, 2024). "The localization of GPR75 in primary cilia may help us better understand the function of cilia in obesity and eating behavior in the future." (PMID 39137039, 2024). "Further studies involving specific knockout of Gpr75 in distinct brain regions could provide insights into its role in obesity and anxiety." (PMID 39137039, 2024). "Using cryo-electron microscopy (Cryo-EM), they studied the GPR75-nanobody complex (NbH3) and were able to obtain information about the activation of the receptor, which is crucial information in the race for a new therapeutic agent anti-obesity." (PMID 37375810, 2023). "Protein truncating variants (PTVs) in GPR75 were detected in approximately 4 per 10,000 individuals, who exhibited an average BMI reduction of 1.8 kg/m2, a weight decrease of 5.3 kg, and a 54% lower obesity risk compared to non-carriers." (PMID 40362321, 2025). "Loss of Gpr75 failed to reduce the development of obesity in Adcy3L278H/L278H mice." (PMID 39137039, 2024). "However, in the present study, the loss of GPR75 (Gpr75–/–) failed to inhibit the development of obesity in these chow diet–fed Lepob- and Adcy3-mutant mice." (PMID 39137039, 2024). "Surprisingly, both human and mouse GPR75 were found to be situated in primary cilia, marking GPR75 as the first identified cilia-associated protein whose loss-of-function mutations do not induce obesity but instead lead to leanness in both mice and humans." (PMID 39137039, 2024). "Therefore, targeting the downregulation of GPR75 expression may hold promise as a potential therapeutic strategy for combating obesity." (PMID 39232780, 2024). "Activation of GPR75 and its ligand 20-HETE triggers pro-inflammatory and hypertensive signaling pathways, leading to diabetes, obesity, endothelial dysfunction, cell proliferation, hypertension, and cardiovascular diseases." (PMID 39310267, 2024). "The presence and function of GPR75 suggest that abnormalities in ciliary signaling may not always lead to obesity." (PMID 39137039, 2024). "Interestingly, Gpr75 knockout failed to rescue the obesity phenotype in both crosses." (PMID 39352389, 2024). "Given the implications of these findings, GPR75, GPR56, M3R, and CB1R emerge as promising candidates for novel therapeutic targets in the treatment of diabetes and obesity, especially when combined with liraglutide, and in patients less or unresponsive to liraglutide." (PMID 40342327, 2025).
Obesity (continued). "This suggests that the improved insulin sensitivity observed in Gpr75–/– mice under prolonged HFD feeding was a secondary effect of the reduced adiposity and that the resistance of Gpr75–/– mice to HFD-induced obesity was not due to enhanced insulin sensitivity but rather decreased food intake." (PMID 39137039, 2024).
Hypertension (7 papers, 2021 to 2025). The presence of chronic increased pressure in the systemic arterial system. "The 20-HETE/GPR75 axis has been implicated in the pathogenesis of hypertension via activation of three key signaling pathways." (PMID 40649725, 2025). "In the vascular system, GPR75 is expressed in VSMCs and endothelial cells and is implicated in hypertension development in various animal models." (PMID 40362321, 2025). "Is GPR75 downstream of CYP1A1 also affected by high levels of Hcy, and through what mechanism does GPR75 participate in the occurrence of hypertension?" (PMID 40649725, 2025). "G-protein-coupled receptor 75 (GPR75) is a newly identified member of the GPCR superfamily known to play important roles in hypertension." (PMID 40649725, 2025). "Literature reports also suggest that GPR75 can participate in the occurrence of hypertension by activating the MAPK pathway." (PMID 40649725, 2025). "In a Cyp4a12 transgenic mouse model of 20-HETE-dependent hypertension, Gpr75 knockdown significantly reduced doxycycline-induced blood pressure elevation, decreased ACE expression, and improved endothelial dysfunction." (PMID 40362321, 2025). "The binding of 20-HETE to GPR75 can trigger signaling pathways in vascular endothelial and smooth muscle cells, leading to vascular angiotensin-converting enzyme expression, hypertension, endothelial dysfunction, remodeling, and contraction." (PMID 39310267, 2024). "Reduction of 20‐HETE‐mediated hypertension, vascular dysfunction and vascular remodeling in the GPR75 KO animal model." (PMID 38344397, 2024). "GPR75 is required for 20‐hydroxyeicosatetraenoic acid‐dependent hypertension, and GPR75 knockdown prevented blood pressure elevation, endothelial dysfunction, and vascular remodeling." (PMID 38463394, 2024). "Knocking down Gpr75 expression or blocking its activity may present a promising therapeutic target for hypertension and related cardiovascular conditions." (PMID 40362321, 2025). "Moreover, the 20-HETE signaling can affect vascular function and induce hypertension through the G-protein-coupled receptor GPR75." (PMID 40649725, 2025). "Notably, GPR75 knockout in animal models can inhibit 20-HETE-mediated hypertension, vascular dysfunction, and remodeling." (PMID 39310267, 2024). "Deletion of the GPR75 prevents hypoxia‐induced pulmonary vasoconstriction and hypertension." (PMID 38344397, 2024). "In mice, 20-HETE activation of GPR75 contributes to the development of hypertension knockdown of the expression of GPR75 mimics the effects of 20-HETE inhibitors to prevent the development of hypertension and vascular hypertrophy in a CYP4A12 transgenic mouse model." (PMID 34943862, 2021). "Probable G‐protein coupled receptor 75 (GPR75), a receptor of 20‐HETE, is a novel target for hypertension treatment." (PMID 37746665, 2023). "It suggests that knockdown of GPR75 prevents 20‐HETE‐mediated vascular remodeling and hypertension." (PMID 38344397, 2024).
endothelial dysfunction (6 papers, 2019 to 2025). In vascular diseases, endothelial dysfunction is a systemic pathological state of the endothelium (the inner lining of blood vessels) and can be broadly defined as an imbalance between vasodilating and vasoconstricting substances produced by (or acting on) the endothelium. "Moreover, a 20-HETE receptor, GPR75, has been linked to endothelial dysfunction." (PMID 31514409, 2019). "The binding of 20-HETE to its receptor GPR75 stimulates intracellular Ca2+ levels in ECs, leading to endothelial dysfunction." (PMID 40916438, 2025). "Their findings show that 20-HETE induces endothelial dysfunction and VSMC contraction through GPR75." (PMID 40362321, 2025). "Although GPR75 has been identified as a 20-HETE receptor and contributes to endothelial dysfunction, it remains to be determined if the receptor plays a role in 20-HETE-related cerebrovascular function or in stroke." (PMID 31514409, 2019). "A chemokine CCL5 (RANTES) receptor, G-protein-coupled receptor GPR75 (Gq), was identified to bind to 20-HETE leading to endothelial dysfunction." (PMID 31514409, 2019). "Recent studies have proved that 20-HETE could bind to the G-protein coupled receptor 75 (GPR75) to promote c-Src-mediated-EGFR and trigger the downstream MAPK pathway to induce ACE expression and endothelial dysfunction in human endothelial cells." (PMID 34594219, 2021).
Cirrhosis (3 papers, 2024 to 2025). A chronic disorder of the liver in which liver tissue becomes scarred and is partially replaced by regenerative nodules and fibrotic tissue resulting in loss of liver function. "In contrast, GPR75 mRNA and protein expression increase during fatty liver and steatohepatitis stages but decline significantly in cirrhosis." (PMID 40362321, 2025). "GPR75 mRNA and protein increased in steatosis and steatohepatitis, then dropped significantly in cirrhosis but rebounded in HCC samples." (PMID 39959811, 2024). "Interestingly, GPR75 protein levels mirrored mRNA changes with a 2-fold increase in steatosis but decreased from steatohepatitis to cirrhosis and returned to levels significantly above normal values in HCC, where β-actin was used as a loading control." (PMID 39959811, 2024). "Interestingly, the CYP4A11 and GPR75 mRNA levels increased in steatohepatitis but dramatically dropped in cirrhosis and then increased in patients with HCC." (PMID 39959811, 2024). "Given 20-HETE vasoconstrictive and pro-inflammatory bioactions, 20-HETE and GPR75 may play a significant role in the pathogenesis of portal hypertension observed during cirrhosis, portal vein thromboses (PVT), and splanchnic thromboses." (PMID 39959811, 2024). "It is also possible that in cirrhosis, the level of CCL5/RNATES increases to antagonize 20-HETE, leading to a decrease in GPR75 synthesis." (PMID 39959811, 2024). "To understand the role of the CYP4/20- HETE/GPR75 axis in the progression of MASLD, we analyzed the production of 20-HETE in the liver of patients with steatosis, steatohepatitis, cirrhosis, or fatty liver-induced hepatocellular carcinoma." (PMID 39959811, 2024). "The abrupt reduction in CYP4A11 and GPR75 in patients with cirrhosis may also be due to increased 20-HETE, serving as a feedback mechanism via GPR75, leading to reduced CYP4A11 and GPR75 gene expression." (PMID 39959811, 2024). "Understanding the role of the CYP4/20-HETE/GPR75 axis in the progression of MASLD and the effective management of portal hypertension in CLD and cirrhosis may provide new therapeutic avenues to treat these progressive liver diseases." (PMID 39959811, 2024). "Therefore, future studies investigating the physiological and pathological roles of hepatic 20-HETE will be critical, as important in the functional relationship of the CYP4 and GPR75 genes in the progression of MASLD and the role in portal hypertension in cirrhosis and CLD." (PMID 39959811, 2024).
liver disease (3 papers, 2024). "This work illustrates key correlations associated with the CYP4/20-HETE/GPR75 axis and the progression of liver disease in humans." (PMID 39959811, 2024). "The 20-HETE/GPR75 activation of the NF-κβ pathway and suppression of endothelial eNOS have important implications for autocrine signaling in sinusoidal homeostasis in CLD, from portal hypertension to vascular thrombosis." (PMID 40452921, 2024).
metabolic syndrome (3 papers, 2024 to 2025). A cluster of metabolic risk factors for CARDIOVASCULAR DISEASES and TYPE 2 DIABETES MELLITUS. "The 20-HETE GPR75 axis has been implicated in cardiovascular, metabolic syndrome, and cancer through its vasoconstriction, insulin resistance, and proliferative properties." (PMID 39959811, 2024).
prostate carcinoma (3 papers, 2020 to 2025). A carcinoma that arises from epithelial cells of the prostate gland. "Further research has established a strong correlation between GPR75 and androgen receptor (AR) expression in prostate cancer (PCa) samples." (PMID 40362321, 2025). "Previously, Hic-5 is increased upon activation of 20-HETE/GPR75 (G-protein coupled receptor 75) that triggering metastatic features of androgen-insensitive prostate cancer cells." (PMID 35625759, 2022).